PPP1R13L (protein phosphatase 1 regulatory subunit 13 like)
Description:
Blocks transcription of HIV-1 virus by inhibiting the action of both NF-kappa-B and SP1. Is involved in NF-kappa-B dependent negative regulation of inflammatory response.
Synonyms: IASPP; NKIP1; RAI; ARCME; CMAEA; RAI4
Tractability: Small molecule: a structure with a bound ligand is known. PROTAC: ubiquitination databases record sites on it.
Gene: Protein-coding gene on chromosome 19 (45,379,634 to 45,406,349, reverse strand). Ensembl gene ENSG00000104881.
Subcellular location: Cytoplasm; Nucleus
Subcellular location (Human Protein Atlas): Cytosol
Gene Ontology:
Molecular function: cadherin binding; identical protein binding; protein binding; transcription corepressor activity
Biological process: negative regulation of inflammatory response; positive regulation of cell differentiation; regulation of transcription by RNA polymerase II; negative regulation of DNA-templated transcription; regulation of DNA-templated transcription
Cellular component: cytoplasm; cytosol; nucleus; nucleoplasm
Genetic constraint (gnomAD): Loss-of-function variants: 47 observed, 61.53 expected, observed/expected ratio (o/e) 0.76, 90% interval 0.6 to 0.97. The synonymous counts are far from expectation, so gnomAD's model fits this gene poorly and the ratio says little. Missense variants: 1,172 observed, 1,009.9 expected, observed/expected ratio (o/e) 1.16, 90% interval 1.11 to 1.22. Synonymous variants: 586 observed, 443.38 expected, observed/expected ratio (o/e) 1.32, 90% interval 1.23 to 1.41.
Gene-disease validity (ClinGen):
ClinGen rates the evidence that PPP1R13L causes each of these diseases.
arrhythmogenic cardiomyopathy with variable ectodermal abnormalities (autosomal recessive): Definitive.
Homologues: Orthologues: chimpanzee PPP1R13L (99% identical), macaque PPP1R13L (98% identical), dog PPP1R13L (91% identical), mouse Ppp1r13l (88% identical), rat Ppp1r13l (88% identical), pig PPP1R13L (82% identical), guinea pig PPP1R13L (79% identical), tropical clawed frog ppp1r13l (41% identical), zebrafish ppp1r13l (32% identical), Caenorhabditis elegans nfki-1 (13% identical).
Diseases named in the same sentence as PPP1R13L in open-access papers:
PPP1R13L is named in the same sentence as 97 diseases in open-access papers, as found by Europe PMC text mining. Sharing a sentence is not in itself a finding about the gene and the disease. The quoted sentences say what the papers report.
melanoma (17 papers, 2014 to 2025). A malignant, usually aggressive tumor composed of atypical, neoplastic melanocytes. "A 2015 melanoma study found that PPP1R13L’s effect on p73 function is primarily evident under cisplatin treatment, with minimal impact in its absence." (PMID 40014097, 2025).
glioma (16 papers, 2017 to 2024). A benign or malignant brain and spinal cord tumor that arises from glial cells (astrocytes, oligodendrocytes, ependymal cells). "Interestingly, miR-124 inhibited the migration and invasion of glioma cells through down-regulation of ROCK1, SOS1, CDK4, STAT3, and PPP1R13L expression, indicating miR-124 may be a valuable biomarker for glioma." (PMID 28060761, 2017).
breast carcinoma (15 papers, 2008 to 2023). "It is located 3' of the gene PPP1R13L and is the polymorphism with the strongest association to postmenopausal breast cancer among Danish women." (PMID 19257887, 2009). "Since its discovery, iASPP was shown to be encoded by the Protein Phosphatase 1 Regulatory Subunit 13-Like (PPP1R13L) gene, which is overexpressed in many tumors including acute leukemia, breast cancer, glioblastoma, ovarian cancer, and head and neck squamous cell carcinoma." (PMID 24714389, 2014). "With the imputed SNPs and haplotype analysis we conclude, as in the previous study, that the maximal association of SNPs with breast cancer in this region was located just 3' of PPP1R13L and do not delimit the position of the causative genetic variant further." (PMID 19257887, 2009).
lung carcinoma (15 papers, 2008 to 2025). "In our genetic epidemiological studies, rs1970764 in oncogene PPP1R13L was most consistently associated with lung cancer risk." (PMID 31483011, 2019). "In our genetic epidemiological fine-mapping studies, the polymorphism rs1970764 in the oncogene PPP1R13L has been most consistently associated with lung cancer risk." (PMID 31483011, 2019). "Special interactions between smoking duration, IL1B rs3136558 and POLR1G rs967591; smoking-duration, IL1B rs1143633, rs3136558 and rs1143630; and IL1B rs1143633, PPP1R13L rs1970764 and POLR1G rs735482 were observed in relation to lung cancer risk." (PMID 37147350, 2023). "We previously reported that PPP1R13L rs1970764, POLR1G rs967591 and rs735482 were associated with lung cancer or interacted in relation to lung cancer risk among both Caucasian Danes and Chinese15–18." (PMID 37147350, 2023). "To compare the DNA methylation status of the PPP1R13L promoter region between lung cancer patients and healthy controls, we conducted this Chinese analytical cross-sectional study." (PMID 31483011, 2019). "Further research using larger sample sizes and a prospective study design is necessary in order to assess the potentially causal roles of these changes to methylation levels at CpG sites in the PPP1R13L promoter region, relating to lung cancer." (PMID 31483011, 2019). "PPP1R13L rs1970764, rs1005165, CD3EAP rs967591, rs735482, rs1007616, rs62109563, and ERCC1 rs3212965 were all associated with lung cancer risk in at least one of the models." (PMID 27183913, 2016). "And we assessed gene–gene or gene–gene–environment interactions between genes of pathway of cytokines and inflammatory response and gene expression (transcription) pathway related to lung cancer risk, including the interaction between IL1B htSNPs, PPP1R13L and POLR1G risk SNPs and smoking-duration." (PMID 37147350, 2023). "Altered levels of DNA methylation in the PPP1R13L promoter therefore might be useful in detection of lung cancer." (PMID 31483011, 2019). "Here, we explored the role of PPP1R13L methylation in lung cancer development." (PMID 31483011, 2019). "We report that in the PPP1R13L promoter region, the methylation levels of some CpG sites in peripheral blood leukocytes differed between lung cancer cases and controls and that hypomethylation was observed more often in lung cancer cases than in controls." (PMID 31483011, 2019). "In this study, seven candidate SNPs in 3′UTR of DRC‐related genes including ERCC1 (rs3212986, rs2336219, and rs735482), OGG1 (rs1052133), MLH3 (rs108621), CD3EAP (rs1007616), and PPP1R13L (rs6966) were analyzed in 300 lung cancer patients and controls from the northeast of China." (PMID 30453383, 2018). "Our study suggests that lung cancer patients have aberrant methylation status (hypomethylation tended to be more frequent) in peripheral blood leukocytes, for several CpG sites in the PPP1R13L promoter region, and that exposure to smoking may influence methylation status in this Chinese population." (PMID 31483011, 2019). "The difference in methylation levels between smokers and nonsmokers among both cases and controls suggested that smoking might lead to lower methylation levels at CpG sites of the PPP1R13L promoter region in peripheral blood leukocytes from lung cancer patients." (PMID 31483011, 2019). "Our study on a Chinese population suggests that lung cancer patients have aberrant methylation status (hypomethylation tended to be more frequent) in peripheral blood leukocytes at several CpG sites in the PPP1R13L promoter region and that exposure to smoking may influence methylation status." (PMID 31483011, 2019). "Currently, the role of PPP1R13L methylation in lung cancer development remains unclear." (PMID 31483011, 2019). "SNPs in PPP1R13L and CD3EAP may be associated with lung cancer risk and survival." (PMID 29108262, 2017).
lung carcinoma (continued). "Recent studies of Koreans reported that PPP1R13L rs1970764 was significantly associated with relapse-free and disease-specific survival in a recessive model for rectal cancer and CD3EAP rs967591 AA genotype exhibited lower overall survival of early-stage lung cancer." (PMID 27183913, 2016).
colorectal cancer (9 papers, 2008 to 2023). A primary or metastatic malignant neoplasm that affects the colon or rectum.
cervical cancer (7 papers, 2015 to 2025). A primary or metastatic malignant neoplasm involving the cervix. "Based on data from the GSE52904, survival analysis showed that PPP1R13L is associated with poor prognosis in cervical cancer." (PMID 40014097, 2025). "Here, we identified PPP1R13L as an oncogene associated with the progression of cervical cancer." (PMID 40014097, 2025). "Therefore, to determine whether glycolysis in cervical cancer cells is associated with PPP1R13L expression, we assessed lactate production and glucose uptake in these cells." (PMID 40014097, 2025). "In summary, we underscore the specificity of the PPP1R13L/p63/PTEN axis in cervical cancer and propose that PPP1R13L holds potential as a therapeutic target for cervical cancer treatment." (PMID 40014097, 2025). "The results from these assays demonstrated that PTEN knockdown or overexpression reversed the effects of PPP1R13L knockdown or overexpression on the migration of cervical cancer cells." (PMID 40014097, 2025). "Our results demonstrate that PPP1R13L promotes cervical cancer cell proliferation, epithelial-mesenchymal transition, cycle progression, and glycolysis via the PTEN/AKT/mTOR pathway." (PMID 40014097, 2025). "PPP1R13L mRNA expression was significantly higher in cervical cancer tissues, while PTEN mRNA showed the opposite pattern." (PMID 40014097, 2025). "Our research has revealed that PPP1R13L promotes cervical cancer cell proliferation, EMT, cell cycle and migration by inhibiting PTEN transcription and subsequently activating the AKT pathway." (PMID 40014097, 2025). "PPP1R13L also shows significant differences in expression between tumor and normal tissues in cancers such as cervical cancer, cholangiocarcinoma, and bladder cancer." (PMID 40014097, 2025). "Given the correlation between PPP1R13L and the G2/M checkpoint, we examined the impact of PPP1R13L on the cell cycle in cervical cancer cells." (PMID 40014097, 2025). "Using co-immunoprecipitation combined with western blot, we identified the interaction between PPP1R13L and both TAp63 and ΔNp63 proteins in cervical cancer cells." (PMID 40014097, 2025). "In summary, the results show that PPP1R13L promotes cervical cancer cell proliferation, EMT, cycle progression, and glycolysis through the PTEN/AKT/mTOR pathway." (PMID 40014097, 2025). "In summary, our data indicate that PPP1R13L holds potential in the targeted treatment of cervical cancer." (PMID 40014097, 2025). "Given p63’s specific role in cervical cancer, we have expanded our research to investigate the effects of PPP1R13L on p63." (PMID 40014097, 2025). "To investigate the role of PPP1R13L in cervical cancer cell lines, we first examined the expression of PPP1R13L in cervical cancer cell lines and tested the knockdown and overexpression efficiency in SiHa and HeLa cells." (PMID 40014097, 2025). "Through rescue experiments, we demonstrated that the reduction of PTEN is an indispensable factor in the progression of cervical cancer induced by PPP1R13L." (PMID 40014097, 2025). "Combined with the high expression of p63 and PPP1R13L in cervical cancer, this underscores the importance and uniqueness of the PPP1R13L/p63/PTEN axis in cervical cancer." (PMID 40014097, 2025). "Subsequently, we performed functional assays both in vitro and in xenograft models to assess the impact of PPP1R13L on cervical cancer." (PMID 40014097, 2025).
cervical cancer (continued). "Given this context, PPP1R13L in cervical cancer holds particular significance." (PMID 40014097, 2025). "Previous studies have reported that PPP1R13L promotes cervical cancer progression, yet its precise mechanism remains unclear and warrants further investigation." (PMID 40014097, 2025). "Notably, PPP1R13L has the highest positivity rate in cervical cancer among the 20 tumor types analyzed." (PMID 40014097, 2025). "We demonstrated that PPP1R13L enhances cell proliferation, cell cycle, EMT, and glycolysis in cervical cancer cells by modulating the PTEN/AKT/mTOR pathway." (PMID 40014097, 2025). "To explore the clinical significance of PPP1R13L and PTEN in cervical cancer, we analyzed mRNA expression in cervical cancer tissues (n = 40) and normal cervical tissues (n = 19) from the Affiliated Zhongnan Hospital of Wuhan University using RT-qPCR." (PMID 40014097, 2025). "In light of these, we sought to elucidate the impact of PPP1R13L knockdown and overexpression on the PTEN/AKT/mTOR pathway and its downstream glycolytic enzymes in cervical cancer cells." (PMID 40014097, 2025). "In the research process, it has been reported that PPP1R13L promotes EMT through the microRNA-20a-FBXL5/BTG3 signaling pathway and endows cervical cancer cells with cisplatin resistance." (PMID 32508530, 2020). "In 2017, PPP1R13L was found to induce EMT and cisplatin resistance in cervical cancer." (PMID 40014097, 2025). "In the immunohistochemical staining of DSP, PPP1R13L and ANXA8 in paracancer and cervical cancer tissues, the staining intensity of three proteins in cancer tissues was found to be enhanced, primarily expressed in the cytoplasm and cell membrane compared with paracancer control." (PMID 38952985, 2024). "Given that we have previously discovered that PPP1R13L can induce opposing changes in PTEN levels at the mRNA level, we conducted the following experiments to investigate whether PTEN plays a role in the effects of PPP1R13L on cervical cancer cells." (PMID 40014097, 2025). "Finally, we confirmed that PPP1R13L inhibits the transcription of PTEN by p63, dependent on specific response elements and emphasized the distinct characteristics of the PPP1R13L/p63/PTEN axis in cervical cancer." (PMID 40014097, 2025). "Immunohistochemistry and western blotting of cervical squamous cell carcinoma tissue slices with antibodies against DSP, PPP1R13L and ANXA8 is conducted, hypothesizing these proteins’ fundamental roles in the regulation and progression of cervical cancer cells." (PMID 38952985, 2024). "Additionally, three differential proteins, DSP, PPP1R13L and ANXA8, were selected, and their possible promoting roles in the occurrence and development of cervical cancer were speculated upon." (PMID 38952985, 2024). "However, in non-cervical cancers or non-tumor diseases, the interaction between PPP1R13L and p73 may play a significant role." (PMID 40014097, 2025).
colon cancer (6 papers, 2017 to 2025). "PPP1R13L was first reported to be associated with glycolysis in colon cancer." (PMID 40014097, 2025).
non-small cell lung carcinoma (6 papers, 2010 to 2023). A group of at least three distinct histological types of lung cancer, including non-small cell squamous cell carcinoma, adenocarcinoma, and large cell carcinoma. "This study investigated the association of PPP1R13L rs1005165 and CD3EAP rs967591 with non-small cell lung cancer (NSCLC) risk and survival in Chinese non-smoking females." (PMID 29108262, 2017).
cervical squamous cell carcinoma (5 papers, 2017 to 2025). A squamous cell carcinoma arising from the cervical epithelium. "Furthermore, elevated levels of PPP1R13L are associated with poor prognosis in both cervical squamous cell carcinoma and cervical adenocarcinoma." (PMID 40014097, 2025).
cardio-cutaneous syndrome (4 papers, 2017 to 2024). "In recent years, PPP1R13L variants have been identified in patients with cardio-cutaneous syndrome, cattle woolly haircoat syndrome, DCM, and ACM." (PMID 35933355, 2022). "PPP1R13L encoding the iASPP protein was identified as the novel gene underlying this human cardio‐cutaneous syndrome." (PMID 28069640, 2017).
heart failure (3 papers, 2017 to 2023). Inability of the heart to pump blood at an adequate rate to meet tissue metabolic requirements. "The analysis revealed that heart failure samples had significantly higher expression levels of EGFL7, SDSL, PPP1R13l, SMTNL2, MFAP4, and TAGLN genes, which may promote the development of heart failure." (PMID 38250028, 2023).
lung adenocarcinoma (3 papers, 2020 to 2025). A carcinoma that arises from the lung and is characterized by the presence of malignant glandular epithelial cells. "Furthermore, knockout of the short isoform of PPP1R13L (gene name for iASPP) in A549 lung adenocarcinoma cells resulted in knockdown of full length iASPP as well as transcriptional changes consistent with immunomodulatory activity." (PMID 36746936, 2023). "Since PPP1R13L has been reported to be associated with cisplatin resistance and the IC50 decline after knocking down CDC20 was relatively small, this study explored the role of CHAF1B on cisplatin sensitivity in lung adenocarcinoma cells." (PMID 32508530, 2020).
Arrhythmia (2 papers, 2020 to 2022). Any cardiac rhythm other than the normal sinus rhythm. "Additionally, deep RNA sequencing identified 17 downregulated genes and 5 upregulated genes in DOX+ mice, among which Ppp1r13l, Clcn1, and Agt have previously been linked to arrhythmias." (PMID 32260593, 2020). "Interestingly, three of these genes, Ppp1r13l, Clcn1 and Agt have been previously linked to cardiac arrhythmias." (PMID 32260593, 2020).
cardiomyopathy (2 papers, 2012 to 2024). A disease of the heart muscle or myocardium proper. "Abnormalities in the fur and heart were also reported for cattle affected with cardiomyopathy and wooly hair coats (CWH) syndrome that carry a frame-shift mutation in the bovine ortholog of the Ppp1r13l gene." (PMID 22928477, 2012).
osteosarcoma (2 papers, 2019 to 2023). A usually aggressive malignant bone-forming mesenchymal neoplasm, predominantly affecting adolescents and young adults.
cervical tumor (1 paper, 2025). "Additionally, according to GSE151666, HPV-positive cervical tumor tissues exhibited higher PPP1R13L mRNA expression compared to HPV-negative primary cervical tumor tissues." (PMID 40014097, 2025).